IL1B (interleukin 1 beta)
Diseases named in the same sentence as IL1B in open-access papers (continued):
Sharing a sentence is not in itself a finding about the gene and the disease.
colitis (continued). "On the other hand, administration of obestatin failed to affect IL-1β concentration in the mucous membrane in rats without colitis." (PMID 26798415, 2016). "Indeed, inhibition of caspase-1 with belnacasan obviously reduced the mature IL-1β level in colon tissue and largely prevented the deteriorating role of DCA in the DSS-induced colitis." (PMID 27965665, 2016). "In rats without colitis, administration of ghrelin for six or 13 days after rectal enema with saline had no impact on the concentration of interleukin-1β (IL-1β) or tumor necrosis factor-α (TNF-α) in the mucosa of the colon." (PMID 27598133, 2016). "Administration of Mutaflor after induction of colitis was without significant effect on mucosal concentration of IL-1β or TNF-α in the colon." (PMID 27433160, 2016). "Seven days later, mucosal concentration of IL-1β and TNF-α in the colon of rats treated with saline after induction of colitis was still significantly elevated and reached a value around two-fold greater than that observed in saline-treated animals without colitis." (PMID 27598133, 2016). "In our study, the RT-PCR assay exhibited that the mRNA levels of TNF-α, IL-1β, and IL-6 were greatly reduced by CBS in DSS-induced colitis mice, suggesting that the protective effect of CBS against colonic injury is related to the regulation of TNF-α, IL-1β, and IL-6." (PMID 26579201, 2015). "The results show that MMF significantly inhibited mRNA expression of pro-inflammatory cytokines IFN-γ, TNF-α, IL-12, IL-6, and IL-1β in mice with TNBS-induced colitis; however, MMF did not inhibit the expression of IL-10 mRNA." (PMID 26561804, 2015). "Lamina propria macrophages of EPRAP-deficient mice exhibited marked increases in the mRNAs corresponding to TNF-α, IL-1β, IL-6, CXCL1, and MCP-1 relative to those of WT mice, indicating that EPRAP contributes critically to inhibiting macrophage activation and colonic inflammation." (PMID 26439841, 2015). "We hypothesized that TNBS colitis would result in HIF-1α activation, particularly within the epithelium, resulting in increased expression of pro-inflammatory cytokines such as IL-1β and TNF-α, and higher levels of iNOS." (PMID 25926972, 2015). "We investigated whether 2-Cl-IB-MECA administration alters the production of pro-inflammatory cytokines, including TNF-a and IL-1β, in colon epithelia of DSS colitis mice." (PMID 25762375, 2015). "Also, in our study, oral enoxaparin reduced the levels of a number of mucosal cytokines including IL-1α, IL-1β, IL-10, MIP-1α, MIP-1β, G-CSF, GM-CSF during colitis." (PMID 26218284, 2015). "Furthermore, the secretion of biologically active IL-8 and IL-1β is mediated by caspase-1, which has been reported to play a role in DSS-induced colitis." (PMID 26484345, 2015). "Furthermore, GL-V9 successfully prevented colitis by inhibiting the elevated levels of IL-1β, IL-6 and TNF-α in serum and the high-production of IL-1β, IL-6, TNF-α, MIP-1α and IFN-γ in colons." (PMID 26327408, 2015). "Specifically, mice with proximally spread, but not distally contained, colitis have increased IL-1β, IL-6, IL-17, TNFα, and IFNγ combined with decreased IL-10 in the distal colon." (PMID 26121642, 2015). "Compared with the TNBS model group, the DAI scoring, plasma and colonic mucosa Hcy levels, MPO activity and contents of MDA, IL-1β, IL-6, TNF-α, MMP-2, MMP-9 in colon and EB in small intestine were significantly increased in the TNBS-induced colitis rats with simultaneous Hcy injection (P < 0.01)." (PMID 24787389, 2014). "In this study, the DAI and HI scores, MPO activity in colonic tissues, as well as the MDA, TNF-α, IL-1β, and IL-6 levels, were simultaneously increased in TNBS-induced colitis rats with Hcy injection, indicating that Hcy can aggravate the oxidative and inflammatory damage in rats with colitis." (PMID 24787389, 2014). "Proinflammatory cytokine IL-1β, which is secreted mainly by macrophages, may contribute to the tissue damage seen in DSS-induced colitis." (PMID 25120575, 2014).
colitis (continued). "Interestingly, both IL-1β and TNF play a prominent role in extra-intestinal thrombosis in animal models of colitis." (PMID 24497828, 2014). "In this paper, colitis was induced using dextran sodium sulfate (DSS) in a cHS4I-hIL-1βP-Luc transgenic mouse, in which the expression of luciferase reporter gene was under the control of the human IL-1β gene promoter." (PMID 23577872, 2013). "LMWH may act on upstream cytokine pathways, reduce the expression of inflammatory cytokines (such as IL-1β and IL-10) and thus alleviate the inflammation reactions in DSS-induced colitis." (PMID 23874391, 2013). "Furthermore, developing a method to monitor real time IL-1β activity in vivo would provide a unique opportunity to assess the precise progression of intestinal inflammation, using a DSS induced colitis model." (PMID 23577872, 2013). "Colitis-induced upregulation of TNF-α, IL-1β, and IL-6 occurred predominantly in the SVF." (PMID 24386254, 2013). "Indeed, several biologic agents that block the actions of IL-1β and TNF-α have been successfully used in experimental colitis models." (PMID 23125487, 2012). "In both models, ciprofloxacin failed to protect against development of colitis and failed to attenuate colonic influx of neutrophils or expression of signature cytokines such as TNFα and IL-1β in a GP-BAR1-dependent manner." (PMID 22046243, 2011). "Thyme essential oil, mainly constituted by p-cymene and thymol, only at high concentrations (5,000 mg/L) significantly inhibited total mRNA IL-1β expression in the mouse colon in which colitis was induced by TNBS, not inhibiting significantly IL-6 expression." (PMID 21160452, 2010). "B. vulgatus mpk mono-colonized mice only showed expression of IL-6 mRNA, whereas E. coli mpk mono-colonized mice, prone to develop colitis and SPF IL-2−/−-mice already suffering from colitis, revealed high levels of IL-1α, IL-1β, TNF-α, IFN-γ, IL-10 and IL-6 mRNA in the intestine." (PMID 18545662, 2008). "The colitis, developed after TNBS administration, largely enhanced the expression of TNF-α, IL-6, IL-1β, IL-12, IL-23, IL-17, Cox-2, IL-10, and IFNβ genes, with a fold increase in mRNA levels of 28.7, 89.26, 303.9, 36.03, 9.14, 329.00, 32.07, 10.89, and 24.16, respectively compared to healthy mice." (PMID 17375199, 2007). "In conclusion, pro-inflammatory cytokines IL-1β and TNFα are considered to be primary mediators, whereas PAF, eicosanoids and NO may reflect secondary mediators in experimental colitis." (PMID 18475637, 1995). "Moreover, SN38-PLGA markedly alleviated colitis severity, as demonstrated by improved body weight, increased colon length, reduced disease activity and histological scores, and lower serum levels of TNF-α, IL-1β, and IL-6 compared with free SN38 or saline." (PMID 42099549, 2026). "Moreover, given the intense inflammatory response characterizing colitis, we examined the gene expressions related to inflammation in colon tissue, including tumor necrosis factor α (TNF-α), interleukin-6 (IL-6), and interleukin-1β (IL-1β)." (PMID 40000617, 2025). "Recent findings showed that PKM2 de-adhesion of SIRT5 significantly reduced the levels of IL-1β produced by macrophages, which in turn ameliorated dextran sulfate sodium salt (DSS)-induced colitis in mice, suggesting that PKM2 could be an effective target for the treatment of IBD." (PMID 40243444, 2025). "Furthermore, HD-SD treatment significantly ameliorated the disease severity of acetic acid (AA)-induced colitis in rats, as evidenced by improved clinical signs, attenuated histological damage, and decreased levels of inflammatory factors (TNF-α, IL-6, and IL-1β)." (PMID 41008224, 2025). "In the DSS-induced colitis model in dogs, significant correlations were observed between specific microbiota and SCFAs (e.g., acetic acid, propionic acid, butyric acid, isovaleric acid, valeric acid, hexanoic acid), as well as pro-inflammatory markers (LPS, TNF-α, IL-1β)." (PMID 40395807, 2025).
colitis (continued). "Colitis did not change the IL-1β amount in the testes compared to the control group." (PMID 40283981, 2025). "Isobutyric acid pretreatment significantly downregulated pro-inflammatory gene expression (IL-1β, TNF-α, NLRP3, and ASC) while upregulating tight junction components (occludin, claudin-1, and zo-1), demonstrating its protective role against DSS-induced colitis." (PMID 41171006, 2025). "The relative mRNA expression of pro-inflammatory factors (IL-1β, TNF-α, and IL-18) was significantly increased in the DSS group compared to the CON group (p < 0.05), indicating a disruption in the balance of inflammatory factors and impaired intestinal immunity in the colitis mice." (PMID 41227621, 2025). "Furthermore, in a DSS‐induced colitis mouse model, UMSC treatment decreased the proportion of Th1 and Th17 cells and down‐regulated the expression of inflammatory cytokines, including IFN‐γ, IL‐1β, IL‐6, IL‐17, as well as TNF‐α at the mRNA levels." (PMID 40842289, 2025). "Furthermore, the SOD3-mediated, anti-inflammatory role in skin inflammation by inhibiting the expression of proinflammatory cytokines, including TNF-α, IL-1β, IL-6, and IL-8, and SOD1-mediated suppression of proinflammatory immune responses against oxidative stress in colitis, were also reported." (PMID 40825682, 2025). "Indeed, our prior preliminary work indicated that A. bisporus WMP pretreatment could reduce IL‐1β and IL‐6, and MPO activity in the proximal colon of a murine DSS‐induced colitis model." (PMID 40509652, 2025). "Another antioxidant was investigated in TNBS-induced colitis in mice—another animal model of IBD; treatment with polyphenolic maqui extract from Aristotelia chilensis improved colonic inflammation and reduced NLRP3 inflammasome activation, IL-1β secretion, and NF-κB activation." (PMID 39451206, 2024). "Our results demonstrated that the cecal gene expression of IL-6, CXCL2 (murine IL-8 homologue), IL-1β, TNF-α, IL-17a, IL-22, and CRAMP (homologue of human cathelicidin LL-37) was significantly elevated in the mice with P. aeruginosa-infected colitis after chemotherapy." (PMID 38397855, 2024). "Furthermore, protocatechuic acid-treated mice exhibited a reduction in the expression of proinflammatory cytokines (IL-6, IL-1β, TNF-α, and cyclooxygenase 2 (COX-2)) in TNBS-induced colitis, achieved by modulating the sphingosine kinase (SphK)/S1P and related signaling pathways." (PMID 38732594, 2024). "In this study, the authors created a model of colitis that did not respond to TNFα, thereby demonstrating that IL-1β expression was another major pathway in the progression of colitis, thus highlighting the importance of IL-1β in UC patients that do not respond to TNFα inhibition." (PMID 39201260, 2024). "The PCA has been reported to inhibit the production of inflammatory mediators, such as IL-6, TNF, IL-1β, and prostaglandin E2 (PGE2), potentially by suppressing the activation of NF-κB and extracellular signal-regulated kinase (ERK) in murine BV2 microglia cells and colitis mouse model." (PMID 38998493, 2024). "Panaxadiol could alleviate DSS induced acute mouse model colitis through suppressing IL-1β secretion and blocking non-canonical caspase-8 inflammasome and MAPKs." (PMID 38698858, 2024). "Treatment with L. casei IB1 improved DSS-induced colitis in mice, as indicated by increased body weight, colon length, and goblet cell numbers and decreased disease activity index (DAI), proinflammatory factor (TNF-α, IL-1β, and IL-6) levels, and histopathological scores after intake of IB1." (PMID 39065147, 2024). "Furthermore, L. edodes polysaccharides have been shown to mitigate weight loss and reduce the expression of pro-inflammatory cytokines such as TNF-α, IL-6, IL-1β and IFN-γ in DSS-induced colitis in mice, suggesting their potential therapeutic efficacy in colitis treatment." (PMID 39130633, 2024).
colitis (continued). "Furthermore, in colitis mice treated with hUC-MSCs, there was a notable decrease in serum levels of IFN-γ, IL-1β, TNF-α and IL-6, as well as reduced the mRNA expression levels of Ifng, Il1b, Tnfa and Il6 in the colons." (PMID 38956621, 2024). "In alcohol-induced colon inflammation, a polyphenol-rich extract of Zhenjiang aromatic vinegar was shown to increase IL-10 and IL-22 levels in the colon of ICR (Institute of Cancer Research) mice exposed to ethanol and also to reduce TNF-α, IL-6, IL-1β, and LPS levels." (PMID 38247489, 2024). "In addition, other authors also demonstrated that a new polysaccharide isolated from HE (HEP10) suppressed the LPS/DSS-induced production of iNOS and COX-2 and proinflammatory mediators such as TNF-α, IL-6 and IL-1β, as well as NLRP3 inflammasome, in rodent models of colitis and in macrophages." (PMID 38671931, 2024). "On the other hand, pretreatment of SPF mice with butyrate before induction of DSS colitis (2BT + DSS group) did not mitigate the impact of DSS on the expression of IL-1β, although we observed significant reduction in the effect of DSS on crypt length, compared to mice of DSS group." (PMID 38595917, 2024). "Moreover, aesculin and aesculetin, another two natural compounds of FC, were proved to relieve the symptoms of DSS-induced colitis, restrain the secretion of TNF-α, IL-1β through inhibiting the activation of NF-κB and MAPKs pathway in colonic tissues and macrophages." (PMID 37161415, 2023). "Oral administration of OA in a mice model of colitis significantly inhibited colon shortening and myeloperoxidase activity, displayed potent anti-inflammatory properties by reducing the activation of TNF-α, IL-1β, IL-17, NF-κB, and MAPK, and increasing the expression of IL-10." (PMID 36829984, 2023). "The level of IL-1β was found to correlate with disease indices, and high levels of IL-1β may indicate acute injury, while IL-1β gene fragment deletion and blockage of mediated signaling pathways both contribute to the alleviation of DSS-induced colitis symptoms." (PMID 36613442, 2023). "Additionally, POL has been shown to effectively attenuate DSS-induced colitis by inhibiting oxidative stress responses, such as nitric oxide and superoxide dismutase, as well as reducing the levels of pro-inflammatory cytokines like TNF-α, IL-1β, and IL-6." (PMID 37653406, 2023). "Expression of NF-κB, TLR4, Myd88, and downstream molecules such as TNF-α, IL-6, and IL-1β was effectively reduced by SGP-H, which improved the secretion of anti-inflammatory cytokines including IL-20 and IL-10 in the colon tissue and serum of DSS-induced colitis mice." (PMID 37836386, 2023). "Based on these observations, increased IL-1β in the colonic LP due to non-canonical inflammasome activation could explain the exacerbation of DSS-induced colitis in VAD mice." (PMID 37240022, 2023). "Notably, patients treated with a combination of anti-CTLA-4 and anti-PD-1 drugs who developed ICI-induced colitis overexpressed mucosal IL-1β (as well as IL-17), but not TNF-α, with a higher abundance of Bacteroides intestinalis." (PMID 36900420, 2023). "It has been indicated that IL-1β could be a target for potential clinical intervention in patients with colitis who have not responded to the neutralization of TNFα." (PMID 36118873, 2022). "These colitis mice also showed a shorter colonic length, increased colonic weight and index of colonic weight, DAI, and pathological damage score, as well as increased levels of pro-inflammatory cytokines TNF-α, IL-1β, IL-6, and IL-12p70, and decreased the level of anti-inflammatory cytokine IL-10." (PMID 36310616, 2022). "The severe acute colitis in AKR1B8 KO mice is featured with high bacterial penetration into mucosa and distant organs, hyper-infiltration of basophils and neutrophils, and activation of innate TLR4 signaling pathway and subsequent production of inflammatory cytokines IL1β and IL6." (PMID 36518763, 2022).
colitis (continued). "Also, in GF mice, the IL-1β mRNA expression was slightly but not significantly increased in the liver of mice with DSS-induced colitis (DSS, group 2) compared to control healthy mice (CT, group 1)." (PMID 36232929, 2022). "Exosomes from hucMSCs reduced the expression of the proinflammatory cytokines TNF-α, IL-1β and IL-6 in the colon in IBD mice, increased the expression of the anti-inflammatory cytokine IL-10 and attenuated the inflammatory response, thereby alleviating DSS-induced colitis in mice." (PMID 36045437, 2022). "In mice colitis models, we demonstrated that orally administrated of TDNPs 2 could ameliorate mice colitis and accelerate colitis resolution via regulating the expression of the pro-inflammatory cytokines, including TNF-α, IL-6, and IL-1β, and antioxidant gene, HO-1." (PMID 35488343, 2022). "DSS increases the production of pro-inflammatory mediators TNF-α, IL-1β, IL-6, IFN-γ and chemokine KC and macrophage inflammatory protein-2, which not only play important role in the pathogenesis of DSS-induced colitis, but also serve as crucial intervention targets for colitis." (PMID 36389828, 2022). "In addition, prophylactic administration of EGCG could reduce the levels of plasma IL-1β, IL-6, IL-8, and TNF-α in mice with colitis induced by DSS, indicating that EGCG can alleviate the symptoms of colitis, colonic injury, and inflammation." (PMID 35276917, 2022). "In fact, glucosamine improved colitis symptoms in DSS-treated mice by preventing intestinal epithelial cell activation and tight junction proteins expression decrease, with a parallel decrease in the nuclear factor-kappa B (NF-kB) activity and reduced TNF-α and IL-1β release." (PMID 36009057, 2022). "Moreover, cholecystectomy also reduced mRNA levels of pro-inflammatory cytokines (Il1β, Il6, Tnfα); while it did not affect anti-inflammatory cytokines (Il4, Il10) in colonic tissues under colitis status." (PMID 36050867, 2022). "In addition to Th17 cells, the IL-1β-ERK-RORγtS182 axis is required for maintaining a subset of the RORγt+ Treg populations in the steady-state colon, as well as regulating their anti-inflammatory cytokine IL-10 production capacity during colitis." (PMID 35294872, 2022). "Moreover, a previous study showed that oral administration of the AhR agonist β-naphthoflavone decreased DSS-induced colitis severity and the production of pro-inflammatory cytokines, such as tumor necrosis factor (TNF)-α, IL-6, and IL-1β, which was consistent with our results." (PMID 36613665, 2022). "The decreased expression of proinflammatory cytokine and increased expression of anti-inflammatory cytokine were also observed in the miR-200b-3p- and miR-181b-5p-treated colitis groups, including IL-6, IL-1β and IL-10, but no significant changes in IL-22 was observed." (PMID 36176029, 2022). "Moreover, the same study found that the expression levels of TNF-α, IL-1β, and IL-12 in DSS-treated colitis mice increased drastically and were significantly, though only partly, reversed by transanal administration of heat-killed Levilactobacillus brevis SBC8803." (PMID 36558391, 2022). "Research in murine models of dextran sulphate sodium (DSS)-induced colitis showed that administration of cocoa FGM-derived polyphenols led to significant abrogation of intestinal length reduction, accompanied by a significant drop of TNF-α and IL-1β in the inflamed colon." (PMID 33806061, 2021). "Interestingly, HIF-2α deletion in a mouse model of moderate DSS-induced colitis was shown to be protective, whereas genetic HIF-2α overexpression in intestinal epithelial cells resulted in spontaneous DSS colitis via increased expression of TNF-α, IL-1β, and IL-6." (PMID 34571989, 2021).